Y_RNA (Y RNA )
Gene: Miscellaneous RNA gene on chromosome 18 (21,724,119 to 21,724,229, forward strand). Ensembl gene ENSG00000200750.
Homologues: Orthologues: macaque Y_RNA (100% identical), chimpanzee Y_RNA (95% identical). Paralogues in human: Y_RNA (84% identical), Y_RNA (81% identical), RNY3P1 (80% identical), Y_RNA (80% identical), RNY3 (79% identical), Y_RNA (79% identical), RNY3P14 (78% identical), Y_RNA (78% identical), RNY3P5 (77% identical), Y_RNA (77% identical), Y_RNA (76% identical), RNY3P11 (75% identical), and 88 more.